CD4 (CD4 molecule)
Diseases named in the same sentence as CD4 in open-access papers (continued):
Sharing a sentence is not in itself a finding about the gene and the disease.
tumor (continued). "In humans, CD4 CTL numbers increase in response to chronic viral infection, anti-tumor responses and several autoimmune diseases." (PMID 39090138, 2024). "Although IEL CD4+ T cells alone showed low cytotoxic activity, old IEL CD3+ T cells showed higher cytotoxic activity against tumor organoids than that of young IEL CD3+ T cells." (PMID 38327516, 2024). "Via flow cytometry, the proportions of CD4+ T cells and CD8+ T cells in the BEV@BMDCs group dramatically raised 21.7‐fold and 16.3‐fold in tumor tissues compared with the control group, respectively." (PMID 39021327, 2024). "Correspondingly, a significant increase in T lymphocytes (CD45+CD3+) within the mouse tumor tissue was detected, particularly the proportions of CD8+ T cells and CD4+ T cells." (PMID 40630838, 2024). "Ex vivo analyses of the treated TME found that mPH-762 provided dose-associated on-target significant reduction of PD-1 surface protein on tumor CD45+ TILs, including CD8+ and CD4+ T cells." (PMID 39697325, 2024). "The resulting T cells were termed T-helper tumor (Tht) cells, characterized by CXCL13+, PD-1+, and CD4+, and were present in NSCLC, melanoma, and breast cancers." (PMID 38261139, 2024). "CD8+ TILs, PD‐L1 expression, and accumulation of CD4+CD25+FOXP3+ Tregs are involved in immune homeostasis, tumor proliferation, and metastasis." (PMID 39264227, 2024). "Anti-tumor therapies which are suggested to significantly suppress tumor growth were totally considered to increase the CD44lowCD62Lhi memory T cells and CD44hiCD62Lhi TCM cells of the tumor-infiltrating CD4 and CD8 T cells in breast cancer." (PMID 39076974, 2024). "Combination therapy with anti-PD-L1 and compound 968 results in increased secretion of granzyme B, CXCL10, and CXCL11 by CD4 + and CD8 + T cells, thereby bolstering CD3 + T cell infiltration into tumor microenvironments." (PMID 38459595, 2024). "Tumor-infiltrating immune cells were analyzed, and the NAPSL.p@OVA groups showed significantly increased CD3+CD4+ and CD3+CD8+ T cell infiltration in tumor tissues compared to the control group." (PMID 38764014, 2024). "Then, we evaluated the correlation between expression of LGALS3 in tumor and gene expression levels of FOXP3, CD4, and CD8 in tumor and stroma area samples that were microdissected from FFPE samples." (PMID 37567864, 2024). "This conversion enables increased infiltration of CD68+ macrophages, CD4+ and CD8+ T cells, CD11c+ dendritic cells, and CD4+ granzyme B into the tumor." (PMID 38962005, 2024). "The deletion of BATF in CD8+ T cells impaired tumour clearance, while BATF overexpression promoted the effector function, improving tumour control independently of CD4+ helper T cells." (PMID 39169517, 2024). "OVA antigen-carrying cancer cell-derived EVs induced OVA-specific CD4+ and CD8+ T cell-mediated immune response, significantly inhibiting tumor growth." (PMID 38243280, 2024). "It’s important to note that mature CD4+ or CD8+ T cells perform distinct functions in different tumors, underscoring the complexity and diversity of the tumor immune landscape." (PMID 39286258, 2024). "Collectively, these results suggest that CD8 + T and NK cells are necessary for the tumor inhibition and eradication induced by CCL11-E6E7 immunotherapy and CD4 + T-cell help the expansion of specific CD8 + T cells and durable remission." (PMID 38459592, 2024). "The positive rate of CD4, CD45RO, and CD68 was higher, while the positive rate of CD20, CD27 and CD8 was lower in tumor tissues than those in corresponding non tumor tissues, which was coincident with the result of immune infiltration analysis." (PMID 38532632, 2024). "Tregs secrete inhibitory cytokines like IL-10, TGF-β, and IL-35 to suppress the cytotoxicity of tumor-specific CD8 T cells, hamper antigen presentation by DCs, and hinder CD4 helper T-cell function." (PMID 38785789, 2024).
tumor (continued). "Fecal transfer from healthy individuals to colorectal tumor-bearing mice enhanced anti-tumor immunity and disease suppression by increasing the infiltration of immune cells (CD8+ and CD4+ T cells and NK cells) targeting tumor cells." (PMID 39766170, 2024). "Looking into CD4+ T lymphocytes subpopulations, it was observed an evident Th2 and Treg cell predominance in NSCLC stroma and tumor epithelium, with lower numbers of Th1, Th17, and Tfh." (PMID 38690280, 2024). "It has been observed that treatment significantly increased the infiltration of CD4+ and CD8+ T cells in the tumor microenvironment, indicating an enhancement of the anti‐tumor immune response." (PMID 39554345, 2024). "Secondly, IL-17A inhibits CD4+ and CD8+ T cell infiltration in some tumor types and promotes infiltration of immune cells that exhibit immunosuppressive functions, like regulatory T cells and myeloid-derived suppressor cells." (PMID 39411241, 2024). "Higher levels of pks+E. coli were associated with decreased serum CRP levels and reduced densities of CD4+ cells and CD163+ cells in the tumor-immune microenvironment." (PMID 39272861, 2024). "Assessment of paired tumor biopsy samples from three patients by immunohistochemistry showed that treatment with mivavotinib resulted in changes in population numbers of CD8, CD4, Treg, NK, and B cells in the tumor." (PMID 38501219, 2024). "In the tumor compartment, we found that carcinoma cells comprised approximately 50% of all cells, with CD8+ T cells representing 1.5%, CD4+ T cells 5.6%, and macrophages 3.9%." (PMID 38429349, 2024). "The PD-1 expression on CD4 and CD8 T cells infiltrating the tumor tissue was increased compared to those isolated from the spleen but without significant changes caused by treatments." (PMID 39000582, 2024). "Apoptosis of tumor cells, the ratio of CD8+/CD4+ in CD3+ cells, CD80+CD86 in DD11c+ cells, and IFN-γ+ in CD3+ all were significantly higher than challenge with IL-2 or the microorganism alone." (PMID 38585738, 2024). "Immunohistochemical assays were employed to gauge the expression levels of CD4, CD8, and Foxp3, thereby providing insights into the dynamics of tumor-infiltrating lymphocytes within the tumor microenvironment." (PMID 39687297, 2024). "By contrast, at the tumor–stromal interface, neighborhood analysis indicated a spatial clustering of immune cells, including CD8+ and CD4+ T cells, neutrophils, DCs and macrophages." (PMID 38338669, 2024). "The presentation of TAAs by APCs can activate adaptive immune cells either locally or in the lymph nodes, resulting in lymphocyte infiltration of activated CD4+ and CD8+ T cells into the tumour." (PMID 38732225, 2024). "Flow cytometry revealed significantly decreased infiltration of MDSCs and M2-macrophages along with an increased proportion of CD4+, CD8+ T cells as well as CD103+ DCs, suggesting a potentiated anti-tumor immune response." (PMID 38609922, 2024). "Our studies have shown that chronic HS diets upregulated the expression of CTLA4 in tumor-infiltrating CD8+ and CD4+T cells in both murine models." (PMID 38891044, 2024). "The CD4+ T cells, CD8+ T cells, and Treg cells were gathered around blood vessels, with only a few infiltrating lymphocytes in the tumor tissue." (PMID 39723389, 2024). "The infiltration of CD4+ and CD8+T cells is the basis of anti-tumor immune response and induces tumor cell apoptosis through interaction." (PMID 39659783, 2024). "The positive correlations were observed between SPOP expression and infiltration levels of CD4+ T cells and CD8+ T cells, implying the key role of SPOP in regulating tumor microenvironment." (PMID 39074086, 2024).
tumor (continued). "Analyses of the cellular make up of tumor-infiltrating leukocytes detected a reduced percentage of FoxP3+ (p = 0.001) CD4+CD25+ cells and IL-10+ (p = 0.0001) CD4+CD25+FoxP3+ cells in metformin-treated mice compared to the non-treated group." (PMID 38892058, 2024). "As most of the tumor-infiltrating immune cells were CD45RO+ cells, and the majority of the CD4+ cells are macrophages, this would imply that the macrophages within the tumor microenvironment are in an inflammatory or activated state." (PMID 39682129, 2024). "Taken together, these data imply that Hes1 on TAMs promotes tumor growth in a way that limits the activities of CD4+ and CD8+ T cells and represents a promising therapeutic approach, especially when combined with existing anti-tumor therapies." (PMID 39702544, 2024). "When Ipatasertib and anti‐PD1 therapies were combined, both the tumour volume and mass exhibited a notable reduction, while the expression of CD45+CD8+ T cells increased, and that of CD45+CD4+CTLA4+ and CD45+CD4+PD1+ T cells decreased." (PMID 39556022, 2024). "In a recent study, in iCCA tumor sites, two immune subpopulations including immunosuppressive CD39+Foxp3+CD4+ Tregs and immune exhausted-like CD39+PD-1+CD8+ T cells were identified correlating with a worse clinical prognosis." (PMID 39766138, 2024). "An increase in PD1+CD8+ T cells, which has been shown to contain a pool of systemic tumor-specific T cells, and PD1+CD4+ T cells was also observed in response to CXCL9/10-DC, with the highest magnitude following combination therapy." (PMID 38518770, 2024). "The presence of CD8+ (cytotoxic T-cells), CD4+ (helper T-cells), and CD25+ (Tregs) tumor-infiltrating lymphocytes (TILs) was quantified in the tumor samples by immunohistochemistry." (PMID 39769460, 2024). "The immune populations of 235 PDAC patients were processed by mIHC for a panel of myeloid and lymphoid cell markers encompassing CD8+ T cells, CD4+ T cells, CD16+/CD163− (M1) macrophages and CD16+/CD163+ (M2) tumor-promoting macrophages." (PMID 38730319, 2024). "Next to KPCY and KPCY55 tumor cells, we identified GPR55 in numerous immune cells of the TME (CD4+ and CD8+ T cells, macrophages, and CD11b+ myeloid cells) indicating a role for GPR55 in immune cell functions, such as migration and cytokine release." (PMID 39885986, 2024). "Platelets in NSCLC patients also express PD-L1, which inhibits CD4 and CD8 T cells and contributes to tumor immune escape.Tumor cell-induced platelet aggregation (TCIPA) is another factor that impacts malignancy in CTC-platelet interactions." (PMID 38974237, 2024). "Recent studies have highlighted the important role of tumor-infiltrating lymphocytes (TILs), specifically CD8 + cytotoxic T cells and CD4 + T cells, in the ICB treatment response." (PMID 38918836, 2024). "In-depth subtyping of tumor-infiltrating T cells by scRNA-seq revealed a decrease in Tregs and a concurrent increase in effector CD8+ and CD4+ phenotypes, including both Th1 and Th2 subtypes." (PMID 38518770, 2024). "Next, we identified different subpopulations of CD4+ and CD8+ T cells in the central, peripheral, and adjacent non-tumor tissues based on CD39 and CD103 expression by manual gating." (PMID 38335302, 2024). "To do this we measured total CD4+ and CD8+ T cells in tumor using multiplex immunofluorescence (mIF)." (PMID 39149474, 2024). "Tumor cell vaccines contain a complete complement of TAA, including epitopes for CD4+ T cells and CTLs." (PMID 38928150, 2024). "ICOS+ Th1-like cells play a crucial role in the antitumor effect of anti-CTLA-4 therapy, constituting the majority of tumor-specific, IFN-γ producing CD4 T cells." (PMID 38517331, 2024). "MC9999 CAR T cells exhibited cytotoxicity against QNS120 and QNS712 tumor cells, as observed through CD8 T cell degranulation, CD4 T cell degranulation, and granzyme B." (PMID 39498357, 2024).
tumor (continued). "Further exploration indicated enhanced survival rates and reduced tumor growth, coupled with an increased number of IFN-γ-induced CD4+ and CD8+ effector T cells alongside decreased number of Tregs and MDSCs." (PMID 39690423, 2024). "Thus, we surmise that the effect of Yap1 inhibition may be mediated through a cancer cell–intrinsic, auto-/paracrine IL-11–dependent mechanism, which may potentially be augmented by a concomitant anti-tumor effect emanating from reduced IL-11 signalling in CD4 effector cells." (PMID 37957015, 2024). "The most important impact of all these mechanisms working together is an increased homing ratio of CD8+ T-cells in the tumor microenvironment (TME), while the number of CD4+, CD25, and regulatory (Foxp3+) T-cells decreases." (PMID 38339258, 2024). "We observed a significant increase in type-I helper CD4+ T cells that produce IFN-γ, which can enhance anti-tumor immunity." (PMID 39702544, 2024). "Specifically, CD40L and IL12 were consistently enriched in CD4+ T cells, CD8+ T cells, γδ T cells, and Treg cells in metastatic UVM, pointing to their importance in modulating immune responses within the tumor microenvironment." (PMID 39916959, 2024). "We observed an expansion of CD4+ T helper and CD8+ T cytotoxic cell populations in TDLNs as well as enhanced tumor infiltration in the 16 Gy + anti-CTLA4 arm." (PMID 39199612, 2024). "We also sought to investigate the correlation between transcription factor expression and the tumor immune microenvironment (TIME) by evaluating CD8+ and CD4+ tumor-infiltrating lymphocytes (TILs)." (PMID 39682568, 2024). "To exclude the impact of PGRN expression by Lewis tumor cells on the TME in PGRN–/– mice, we first compared the expression of PGRN in Lewis cells with that in infiltrating CD4+, CD8+ T cells and macrophages in the TME of WT tumor-bearing mice." (PMID 38744851, 2024). "Simultaneously, tumor‐infiltrating total and activated (CD44hiCD62Llo) CD8+ and CD4+ T cells, were more abundant in Ddr1‐KD tumors, indicating a negative correlation between intratumoral tumor infiltrating lymphocytes (TILs) abundance and DDR1 expression." (PMID 38953306, 2024). "We cultured activated PBMCs, primarily comprising of PD-L1-positve CD4 and CD8 T-cells, with the intention of simulating an immunologically inflamed tumor microenvironment." (PMID 38254876, 2024). "Within the T cell compartment, we observed increased levels of CD8+ T cells and CD4+ TEM cells, but lower levels of Tregs in CR705Parp7KO tumours." (PMID 39867896, 2024). "Across the world, many investigators showed that DC-based vaccines were safe and induced the expansion of circulating CD4+ T cells and CD8+ T cells that were tumor antigen-specific." (PMID 38395948, 2024). "Another study by B. bifidum and Lactobacillus acidophilus demonstrated tumor reduction through the modulation of IFN-γ and IL-10, as well as the activation of CD4 + and CD8 + cells." (PMID 38585690, 2024). "The results demonstrated that the RSL3@LIPO@GEL group accumulated the most abundant M1 macrophages and CD4+ T and CD8+ T cells in tumor tissues compared to the other groups." (PMID 39308160, 2024). "In the CIRT combined with anti-PD-1 group, there was an increase in the infiltration of CD4+ and CD8+ T cells into tumor tissues, leading to significant tumor control and an extended survival period for tumor-bearing mice." (PMID 39091498, 2024). "Interaction with HPV+ OPSCC tumor cells amplifies CXCL13 and IFNγ release in CD4+T cells, fostering a pro-inflammatory TME." (PMID 39105803, 2024). "Among other components of the tumor immune microenvironment (TIME), infiltration by CD8+ T lymphocytes was consistently found to be predictive of response while results concerning CD4+ T cells are controversial." (PMID 39766316, 2024).
tumor (continued). "Listeria monocytogenes is a cancer immunotherapy vector that increases the strength of anti-tumor activities through CD8+ and CD4+ lymphocytes, crossing epithelial living layers and stimulating the immune system." (PMID 39467702, 2024). "The findings indicated that within this NET-rich tumor microenvironment, the majority of CD4+ and CD8+ tumor-infiltrating lymphocytes expressed a variety of inhibitory receptors and exhibited signs of functional and metabolic exhaustion." (PMID 39555072, 2024). "It indicated that senescent tumor cells exhibited remarkable chemotaxis to CD45+ cells, CD4+ T cells, CD8+ T cells, and CD11b+ myeloid cells." (PMID 38323313, 2024). "The results showed that tumor-immune cell regions trended toward expressed SMA, HLA-DR, CD68 and CD4 proteins similarly to the THC regions." (PMID 39499374, 2024). "The tumor eradication is predominantly CD4 T cell dependent, and the major effect of BCG is to enhance the effector functions of tumor-specific CD4 T cells, specifically IFN-γ production." (PMID 39081326, 2024). "PD-L1+ Bregs were found to inhibit proliferation of CD8+ T cells, CD4+ CD25- T cells and CD49b+ NK cells in a murine model, via reduced IFN-γ and TNF-α secretion, which ultimately promoted tumour growth in murine breast cancer models." (PMID 39346706, 2024). "In the tumor draining LNs, there was an early increase in CD8+ T cells and CD4+ Teffs coupled with an overall decrease in Tregs in all treatment groups." (PMID 38957315, 2024). "Antigen-presenting cells promote the transformation of resting T cells into TRegs to promote metastasis, while other studies have shown that they induce CD4+ T cell-dependent CD8+ T cell activation, thereby controlling tumor progression." (PMID 38032223, 2024). "In immunodeficient mice or mice with T cell exhaustion, there was negligible change in tumor volume, indicating that pyroptosis mediated tumor regression required CD8+ CD4+ T cell assistance and was closely related to the host immune system." (PMID 37984863, 2024). "One possible anti-tumor mechanism mediated by CD4+ T cells is CD4+ T cells recognize MHC-II on cancer cells and eliminate the tumor." (PMID 39106430, 2024). "The area positive for CD4+ and CD8+ T cells in the immunofluorescence images of the primary tumor tissue slices was quantified." (PMID 38742454, 2024). "Immunohistochemical characterization identified these cells as CD8+, CD4+, CD20+, FOXP3+, CD163+, or CD68+ cells, and the density of each cell type in the tumor-immune microenvironment (TIME) was quantified." (PMID 39272861, 2024). "In a murine pancreatic ductal adenocarcinoma model, a single UTMC treatment increased tumoral cytoplasmic HMGB1 and enhanced antigen presentation by macrophages, CTLs, and CD4+ cells only in TDLNs at 2 days after UTMC, which resulted in reduced tumor growth." (PMID 38543305, 2024). "Two prospective phase II trials showed that the DC-CIK can induce the proliferation of autologous tumor-specific T cells and the expression of IFN-γ, IL-2, and TNF-α in CD4+ T cells." (PMID 38476223, 2024). "This study revealed low levels of total T(CD3+), CD4+, and CD8+T lymphocyte infiltration in the tumor tissues for both the untreated group and the group treated with anti-PD-1 alone." (PMID 38931345, 2024). "Deletion of CD4+ and CD8+ T cells resulted in a complete rescue of tumor growth, indicating that T cells are necessary for tumor clearance in the absence of Ptges." (PMID 39298269, 2024). "The consequence of this is a reduction in the secretion of TGF-β and IL-10, an increase in type I interferon levels (which activates NK cells, DCs, CD4+ T cells, and CD8+ T cells), stimulation of NK cells, and augmentation of anti-tumor immunity." (PMID 38426090, 2024).